PITX3 (paired like homeodomain 3)
Diseases named in the same sentence as PITX3 in open-access papers (continued):
Sharing a sentence is not in itself a finding about the gene and the disease.
microphthalmia (13 papers, 2007 to 2023). Congenital or developmental anomaly in which the eyeballs are abnormally small. "Mutations in the PITX family gene PITX3 cause congenital cataract and anterior segment mesenchymal dysgenesis, such as corneal opacity, microphthalmia and microcornea." (PMID 33923544, 2021). "This phenotype is reminiscent of the manifestations in the Texel Sheep as this breed displays microphthalmia as an autosomal recessive congenital condition, caused by a missense mutation in the conserved homeodomain of PITX3, c.338G > C, p.(Arg113Pro)." (PMID 24555714, 2014). "This non-synonymous SNP located in PITX3 exon 4 (c.338G>C) showed perfect association to the microphthalmia phenotype." (PMID 20084168, 2010). "The potential impact of this microphthalmia associated substitution was evaluated by multiple species alignment of PITX3 homeodomain." (PMID 20084168, 2010). "In one family with autosomal dominant posterior polar cataract, two siblings homozygous for a deletion mutation in PITX3 exhibited severe microphthalmia and neuro-developmental abnormalities." (PMID 21042563, 2010). "Interestingly, Pitx3 mapped to the aphakia (ak) locus, a recessive mutation resulting in bilateral microphthalmia with lens aplasia originally described by Varnum and Stevens in 1968." (PMID 24555714, 2014). "Apparently, one copy of the PITX3 wildtype allele is sufficient for regulation an undisturbed embryonic lens development, because no visible eye phenotype has been reported in heterozygous carriers of the microphthalmia mutation." (PMID 20084168, 2010). "Association of the PITX3 mutation with the microphthalmia phenotype." (PMID 20084168, 2010). "However, DNA sequencing revealed a non-synonymous mutation in the PITX3 gene, which is perfectly associated with the microphthalmia phenotype in Texel sheep." (PMID 20084168, 2010). "Furthermore, the identification of a naturally occurring PITX3 mutation offers the opportunity to use the Texel as a genetically characterized large animal model for human microphthalmia." (PMID 20084168, 2010). "Our study indicates that coding mutations of the PITX3 gene might also be responsible for rare recessive forms of human isolated microphthalmia." (PMID 20084168, 2010). "Therefore, we initially investigated whether mutations in the ovine PITX3 gene might be responsible for the microphthalmia phenotype." (PMID 20084168, 2010). "Mutations in PITX3 result in congenital cataracts, anterior segment mesenchymal dysgenesis (ASMD), Peter's anomaly, and microphthalmia in humans." (PMID 21698120, 2011). "We designed PCR primers for the amplification of a 14.5 kb segment containing the entire PITX3 gene and determined the genomic sequence of four microphthalmia affected and four healthy control sheep." (PMID 20084168, 2010). "Analyzing inherited isolated microphthalmia/anophthalmia in humans revealed a total of eight genes (SOX2, PAX6, OTX2, RAX, CHX10, FOXE3, PITX3, CRYBA4) carrying causative mutations." (PMID 20084168, 2010). "In addition, mutations in PITX3 are responsible for various ocular defects, including congenital cataract, ASMD, Peters anomaly, and microphthalmia." (PMID 30894134, 2019).
microphthalmia (continued). "PITX3 is responsible for various ocular defects, including congenital cataract, anterior segment dysgenesis (ASD), Peters’ anomaly, and microphthalmia." (PMID 36153513, 2022).
autosomal dominant congenital cataract (4 papers, 2010 to 2024). "Before this finding, the first human PITX3 mutations had already been identified in two families with autosomal dominant congenital cataract (ADCC)." (PMID 24555714, 2014). "The aim of this study was to perform a genetic study of the PITX3 gene in five probands with autosomal dominant congenital cataract (ADCC) and ASD, to compare their clinical presentations to previously reported PITX3-associated phenotypes and to functionally evaluate the PITX3 mutations found." (PMID 24555714, 2014). "Mutations in paired-like homeodomain transcription factor 3 (PITX3), another homeodomain transcription factor located at chromosome 10q25, are associated with autosomal dominant congenital cataract with or without anterior segment dysgenesis." (PMID 20806047, 2010).
mental retardation (3 papers, 2010 to 2023). "But as her mother and one maternal uncle (II:11) also display intellectual disability, this was felt to be unrelated to the paternally inherited PITX3 mutation." (PMID 24555714, 2014). "Taking these results further, we analyzed the PITX3 gene in a Tunisian family with ARCC associated to mental retardation (MR)." (PMID 20376326, 2010). "In previous work, we reported the absence of mutations in four genes (PAX6, PITX3, HSF4 and LIM2 genes) encoding for congenital cataract and expressed in the human brain in Tunisian families with cataract and mental retardation." (PMID 37179318, 2023).
Microcornea (3 papers, 2010 to 2023). A congenital abnormality of the cornea in which the cornea and the anterior segment of the eye are smaller than normal. "For example, mutations in multiple genes have been associated with cataract plus microcornea (e.g., MAF, CRYAA, and GJA8), posterior polar cataract (e.g., PITX3, EPHA2, CHMP4B, and NF2), or sutural cataract (e.g., BFSP2, CRYAB, and NHS)." (PMID 21042563, 2010).
Anxiety (2 papers, 2019 to 2021). Intense feelings of nervousness, tension, or panic often arise in response to interpersonal stresses. "Moreover, Pitx3 mutants show a loss of dopaminergic neurons in the substantia nigra with accompanying increased anxiety-related behavior and reduced locomotor activity." (PMID 30991053, 2019). "Our previous study found that the Pitx3-A53Tα-Syn × Tau–/– triple transgenic mice model of PD showed anxiety-like behavior among 12- to 18-mouth-old, which may be related to the substantial degeneration of PV+ neurons in the SNR." (PMID 35087392, 2021). "In this study, Pitx3-A53Tα-Syn × Tau–/– mice showed specific decreased expression of PV and c-fos in the SNR at old age, which may be correlated with their increased α-syn aggregates and anxiety-like behavior." (PMID 35087392, 2021).
breast carcinoma (2 papers, 2016 to 2023). "Reports have indicated high methylation levels of PITX3 in breast cancer." (PMID 37796202, 2023). "Moreover, PITX3 has previously been found to be aberrantly methylated in breast cancer patients." (PMID 27708722, 2016).
buphthalmos (2 papers, 2011 to 2022). "In summary, we report a novel phenotype characterized by unilateral buphthalmos, corneal staphyloma and corneal fistula this is associated with a PITX3 variant." (PMID 36153513, 2022). "A novel phenotype characterized by unilateral buphthalmos, corneal staphyloma and corneal fistula in an infant were reported to be associated with PITX3 in our study." (PMID 36153513, 2022). "In this case, our aim is to report novel phenotype (unilateral buphthalmos and corneal opacity) of a 4-month-old female infant with variants in PITX3." (PMID 36153513, 2022). "In this case, an infant with unilateral buphthalmos, corneal staphyloma and corneal fistula carrying a variant in PITX3 was reported." (PMID 36153513, 2022).
Corneal opacity (2 papers, 2022 to 2023). A reduction of corneal clarity. "Anterior segment dysgenesis and corneal opacity could be found in 14.53 and 2.13% of patients harbouring PITX3 variants, respectively." (PMID 36153513, 2022).
microcephaly (2 papers, 2010 to 2011). A congenital or acquired developmental disorder in which the circumference of the head is smaller than normal for the person's age and sex. "Until today no candidate gene has been reported responsible for such phenotypes: association between congenital cataract, MR and congenital cataract, MR and microcephaly, so we tried to focus on genes already described in ADCC and/or ARCC and expressed in the human brain (PAX6, PITX3 and HSF4)." (PMID 22103961, 2011). "Based on these observations, we studied the PITX3 gene in a Tunisian family whose two affected members presented ARCC associated with MR and microcephaly but we did not identify any pathogenic mutation." (PMID 20376326, 2010). "But for PITX3 and HSF4 genes although variations were absent in 50 ethnically matched control samples, there is no segregation between these detected polymorphisms and the studied phenotype (association between congenital cataract, mental retardation and microcephaly) in family F1." (PMID 22103961, 2011).
Posterior polar cataract (2 papers, 2011 to 2022). "Half of the PITX3 variants, are represented by a single hot spot in exon 4 at c.640_656dup17bp; p.G220PfsX95 in the c-terminal region of the gene that causes mainly AD posterior polar cataracts and anterior segment dysgenesis in several families around the globe." (PMID 34345029, 2022).
prostate carcinoma (2 papers, 2016 to 2023). A carcinoma that arises from epithelial cells of the prostate gland. "PITX3 promoter methylation also impacts the recurrence-free survival of prostate cancer patients." (PMID 37796202, 2023). "In this study, PITX3 was shown to be aberrantly methylated in prostate carcinomas." (PMID 27708722, 2016).
atrial fibrillation (1 paper, 2017). A disorder characterized by an electrocardiographic finding of a supraventricular arrhythmia characterized by the replacement of consistent P waves by rapid oscillations or fibrillatory waves that vary in size, shape and timing and are accompanied by an irregular ventricular response. "PITX3 is an interesting candidate, as PITX2, a transcription factor from the same family, has been implicated in transcriptional regulation of cardiac ion channel genes and genetic variants close to PITX2 have been associated with atrial fibrillation." (PMID 28903782, 2017).
autism (1 paper, 2023). Persistent deficits in social interaction and communication and interaction as well as a markedly restricted repertoire of activity and interest as well as repetitive patterns of behavior. "The neural system abnormity may be related to PITX3 mutation, but it is not yet certain whether other phenotypes (such as autism and facial features) are related to PITX3 mutation." (PMID 37139083, 2023).
benign prostatic hyperplasia (1 paper, 2016). A non-cancerous nodular enlargement of the prostate gland. "PITX3 was hypermethylated in PCa compared to normal adjacent prostate tissue in the training cohort and compared to both normal and benign prostatic hyperplasia in the test study." (PMID 27708722, 2016).
dependence (1 paper, 2019). "However, after prolonged morphine dependence (three and six weeks), the level of Pitx3 significantly decreased (P < 0.05 for both groups)." (PMID 30634592, 2019). "However, it remains unclear what effects TH, Nurr1, and Pitx3 have on dopaminergic neurons relating to morphine dependence." (PMID 30634592, 2019). "Immunohistochemistry showed that the number of TH+, Nurr1+, and Pitx3+ cells, and the number of TH+ cells expressing Nurr1 or Pitx3, significantly decreased in the VTA after a long period of morphine dependence." (PMID 30634592, 2019).
depression (1 paper, 2022). "It is worth noting that some studies have constructed a depression-PD co-morbidity animal model using Pitx3 (a risk gene of PD) deficient mice or mice treated intraperitoneally with reserpine." (PMID 35645772, 2022).
endometriosis (1 paper, 2021). The growth of functional endometrial tissue in anatomic sites outside the uterine body. "EN1, PITX3, and SHOX2 are involved in neuron formation in eutopic and ectopic tissues, and the altered expressions in these genes may be related to nerve formation and pain sensation in endometriosis patients." (PMID 34470627, 2021).
glioma (1 paper, 2023). A benign or malignant brain and spinal cord tumor that arises from glial cells (astrocytes, oligodendrocytes, ependymal cells). "However, we found 240 TFBS that were present in the promoters of genes overexpressed in GIV gliomas, and this set included binding sites for c-Jun, SCRT2, PITX3, ERR1, or ZN784." (PMID 36850002, 2023).
lung carcinoma (1 paper, 2021). "PITX3 is a member of the PITX gene family, which includes PITX1, PITX2, and PITX3, all of which are related to lung cancer." (PMID 34631307, 2021). "There are few studies on the occurrence and development of PITX3 and lung cancer." (PMID 34631307, 2021). "However, previous studies have shown that the mRNA expression level of PITX3 in lung cancer tissue is not significantly different from normal lung tissue, but it is closely related to tumor stage, and the prognosis of patients with high expression is poor." (PMID 34631307, 2021).
morphine dependence (1 paper, 2019). Strong dependence, both physiological and emotional, upon morphine. "The results of the present study indicated that the expression of TH, Nurr1, and Pitx3 significantly decreased and damage to dopaminergic neurons was clearly visible after prolonged morphine dependence." (PMID 30634592, 2019). "The expression of Pitx3 was significantly upregulated after one week of morphine dependence (P < 0.05)." (PMID 30634592, 2019).
neuroblastoma (1 paper, 2019). Neuroblastoma (NB) is the most common solid, extracranial childhood tumor. "In connection to Pitx3 mRNA expression, the literature has shown that Pitx3 interacts with the promoter of the TH gene improving its transcription in Neuro2A neuroblastoma cells." (PMID 31547185, 2019).
nicotine addiction (1 paper, 2014). "miR-133b negatively regulates the expression of transcription factor, Pitx3, which activates the dopamine receptor (DRD1), a mediator of nicotine addiction in smokers." (PMID 24479666, 2014).
schizophrenia (1 paper, 2016). A major psychotic disorder characterized by abnormalities in the perception or expression of reality. "The Pitx3-miR-133b pathway associated with PD is also implicated in the neuropsychiatric disorder schizophrenia." (PMID 27826551, 2016).
α-synucleinopathies (1 paper, 2024). "This is the first study showing that miR-124-3p decreases PQ-induced α-synuclein levels and the associated NOX1/Rac1 signaling pathway, and impacts PITX3 protein levels, supporting the potential of miR-124-3p as a disease-modifying agent for PD and related α-synucleinopathies." (PMID 38451434, 2024).
tumor (5 papers, 2016 to 2025). "Four genes (CENPH, MYLIP, PITX3, and TRAF3IP3) were eventually identified; these were associated with tumor-infiltrating immune cells, the proliferation of tumor cells, and cell adhesion." (PMID 34631307, 2021). "The PITX3 locus was highly methylated in tumor tissues from the training and the validation cohort." (PMID 28174607, 2017). "Among the five RMScore genes, four (ANLN, KRT6A, PITX3, and NTSR1) were identified to be upregulated, while CYP17A1 was identified to be downregulated in TCGA-LUAD tumor tissues compared with paired normal tissues." (PMID 35859664, 2022). "The comparison of PITX3 methylation in tumor and normal adjacent tissue (NAT) revealed a significant difference between tumor tissue (mean 69.0%, median 71.8%) and NAT (mean 32.1%, median 32.3%; p < 0.001)." (PMID 28174607, 2017). "In detail, high ISUP Gleason grading group, advanced tumor stages, and high preoperative PSA values were related to high PITX3 methylation in both cohorts." (PMID 27708722, 2016). "Other TFs, such as PITX3, RHOXF1, and TBX15, are involved in developmental and organogenesis pathways, suggesting a more plastic tumor phenotype that might support survival in diverse microenvironments." (PMID 41238550, 2025). "PITX3 methylation was significantly higher methylated in tumor compared to normal adjacent tissue (NAT; training cohort: median methylation NAT 32.3%, tumor 71.8%, p < 0.001; validation cohort: median methylation NAT 16.9%, tumor 35.9%, p < 0.001)." (PMID 28174607, 2017).
cancer (2 papers, 2017 to 2022). A tumor composed of atypical neoplastic, often pleomorphic cells that invade other tissues. "To understand whether the expression of PITX genes correlates with cancer, we evaluated PITX1, PITX2, and PITX3 mRNA expression in different human tumors (33 cancer types) and adjacent normal tissues using TCGA data." (PMID 36204311, 2022). "Interestingly, when performing a subgroup analysis among patients with p16-negative tumors, patients with PITX3 hypermethylated tumors revealed an HR of 2.44 ([95%CI 1.44–4.14], p = 0.001) compared to patients with hypomethylated cancers." (PMID 28174607, 2017).
PITX3 also shares sentences with these, for which no sentence is quoted: glaucoma (3 papers); aniridia (2); dementia (2); developmental delay (2); head and neck squamous cell carcinoma (2); autosomal dominant cataract (1); Axenfeld-Rieger syndrome (1); Blindness (1); brain malformations (1); cocaine addiction (1); congenital total cataract (1); DHPR deficiency (1); facioscapulohumeral muscular dystrophy (1); multiple sclerosis (1); neurodegenerative disease (1); Nystagmus (1); Obesity (1); pancreatic cancer (1); periodontitis (1); Peters anomaly (1); Segawa’s syndrome (1); thyroid cancer (1).